MAPK4 (mitogen-activated protein kinase 4)
Description:
Atypical MAPK protein. Phosphorylates microtubule-associated protein 2 (MAP2) and MAPKAPK5. The precise role of the complex formed with MAPKAPK5 is still unclear, but the complex follows a complex set of phosphorylation events: upon interaction with atypical MAPKAPK5, ERK4/MAPK4 is phosphorylated at Ser-186 and then mediates phosphorylation and activation of MAPKAPK5, which in turn phosphorylates ERK4/MAPK4. May promote entry in the cell cycle (By similarity).
Synonyms: ERK-4; p63-MAPK; ERK4; PRKM4; Erk3-related; p63MAPK
Tractability: Small molecule: a high-quality ligand is known; it belongs to a druggable protein family. PROTAC: ubiquitination databases record sites on it; a small molecule that binds it is known.
Target class: CMGC protein kinase group; CMGC protein kinase ERK3; Enzyme; CMGC protein kinase MAPK family; Kinase; Protein Kinase
Gene: Protein-coding gene on chromosome 18 (50,559,451 to 50,731,830, forward strand). Ensembl gene ENSG00000141639.
Subcellular location: Cytoplasm; Nucleus
Subcellular location (Human Protein Atlas): Golgi apparatus; Nucleoplasm; Cytosol; Midbody
Pathways (Reactome):
Signal Transduction: MAPK6/MAPK4 signaling
Gene Ontology:
Molecular function: protein binding; MAP kinase activity; protein homodimerization activity; protein kinase binding; protein serine/threonine kinase activity; ATP binding; protein heterodimerization activity; protein kinase activity; protein serine kinase activity
Biological process: intracellular signal transduction; protein phosphorylation; MAPK cascade
Cellular component: cytoplasm; cytosol; nucleoplasm; nucleus
Genetic constraint (gnomAD): Loss-of-function variants: 22 observed, 41.78 expected, observed/expected ratio (o/e) 0.53, 90% interval 0.38 to 0.75. The upper end of that interval is the gene's LOEUF score, 0.75, which puts it in group 3 of 6, group 1 being the genes least tolerant of losing a copy. Missense variants: 736 observed, 788.36 expected, observed/expected ratio (o/e) 0.93, 90% interval 0.88 to 0.99. Synonymous variants: 390 observed, 348.04 expected, observed/expected ratio (o/e) 1.12, 90% interval 1.03 to 1.22.
Homologues: Orthologues: chimpanzee MAPK4 (99% identical), macaque MAPK4 (99% identical), guinea pig MAPK4 (94% identical), mouse Mapk4 (94% identical), rat Mapk4 (94% identical), dog MAPK4 (92% identical), rabbit MAPK4 (81% identical), tropical clawed frog mapk4 (75% identical), zebrafish mapk4 (60% identical), Caenorhabditis elegans pmk-2 (18% identical), Caenorhabditis elegans pmk-1 (18% identical), Caenorhabditis elegans kgb-1 (17% identical), and 6 more. Paralogues in human: MAPK6 (55% identical), MAPK7 (25% identical), MAPK3 (24% identical), MAPK1 (24% identical), MAPK15 (24% identical), MAPK12 (21% identical), MAPK13 (21% identical), NLK (20% identical), MAK (20% identical), CILK1 (20% identical), MAPK14 (20% identical), MAPK11 (19% identical), and 7 more.
Diseases named in the same sentence as MAPK4 in open-access papers:
MAPK4 is named in the same sentence as 62 diseases in open-access papers, as found by Europe PMC text mining. Sharing a sentence is not in itself a finding about the gene and the disease. The quoted sentences say what the papers report.
glioma (21 papers, 2020 to 2025). A benign or malignant brain and spinal cord tumor that arises from glial cells (astrocytes, oligodendrocytes, ependymal cells). "Conversely, while MAPK4 has been implicated in promoting cell survival and inhibiting apoptosis in certain contexts and cells, such as in glioma cells, its overall role in development appears less critical." (PMID 41560854, 2025). "Nevertheless, there are limitations to finalize the MAPK4 as the novel diagnostic marker and prognostic indicator of glioma." (PMID 36999945, 2023). "Aberrant MAPK4 expression was significantly associated with poor clinicopathological characteristics of glioma." (PMID 36999945, 2023). "Heatmaps were used to display the top 15 genes that are positively and negatively associated with MAPK4 in glioma based on information in the TCGA dataset." (PMID 36999945, 2023). "Circ-MAPK4 served as an oncogene in gliomas, was inversely regulated, and was associated with the clinico-pathological stage of gliomas (p < 0.05)." (PMID 35883576, 2022). "In gliomas, circ-MAPK4 acted as an oncogene, was inversely upregulated and linked to clinical pathological stage of gliomas (P < 0.05)." (PMID 31992303, 2020). "The clinical significance, biological roles and underlying molecular mechanisms through which MAPK4 acts in glioma remain unclear." (PMID 36999945, 2023). "Association between MAPK4 mRNA expression and the clinical parameters of glioma patients in TCGA." (PMID 36999945, 2023). "We present evidence that MAPK4 may be an efficient diagnostic marker and prognostic indicator of glioma." (PMID 36999945, 2023). "In the follow-up study, the overexpression of circ-MAPK4 was found in early neurodevelopment and glioma tissues, indicating that a cancer-promoting effect of circ-MAPK4 in glioma." (PMID 38075205, 2024). "For example, circRNA MAPK4 inhibited cell apoptosis via the p38/MAPK axis by playing the sponge role for miR-125a-3p in glioma." (PMID 38075205, 2024). "In glioma, circ-MAPK4 (has_circ_0047688) was reported to inhibit cell apoptosis by functioning as miR-125a-3p sponge to regulate p38/MAPK signaling pathway." (PMID 38177102, 2024). "Here, we have revealed that MAPK4 is significantly correlated with poor clinicopathological characteristics and disease progression in patients with glioma." (PMID 36999945, 2023). "MAPK4 was significantly related to functional states, including stemness, metastasis, cell cycle, differentiation and proliferation, in glioma at single‐cell resolution." (PMID 36999945, 2023). "Functional states, including inflammation, angiogenesis, proliferation and differentiation, were significantly related to MAPK4 expression in the single‐cell RNA‐seq dataset 2 of glioma." (PMID 36999945, 2023). "MAPK4 silencing inhibited proliferation and migration and induced G1 cell cycle arrest in glioma cells via the AKT/mTOR pathway." (PMID 36999945, 2023). "Our findings shed new light on the potential of MAPK4 as a possible target in the immune regulation of glioma and in immunotherapy." (PMID 36999945, 2023). "MAPK4 functions as a prognostic indicator in glioma and promotes the proliferation and migration of GBM cells through the AKT/mTOR pathway." (PMID 36999945, 2023). "A high level of MAPK4 expression predicted poor prognosis in glioma patients as reflected by OS, DSS and PFI." (PMID 36999945, 2023). "Decreased infiltration of CD8+ T cells in gliomas with arm‐level deletion and decreased infiltration of dendritic cells in gliomas with arm‐level gain were found in GBM compared with gliomas with normal somatic copy numbers of the MAPK4 gene." (PMID 36999945, 2023). "As shown by the gene expression profiles of different cancers, MAPK4 was present at high levels in glioma, accompanied by the enriched expression of MAPK4 in diverse cancers." (PMID 36999945, 2023). "Signaling pathways such as the MAPK, PI3K, focal adhesion‐PI3K/AKT/mTOR, and EGFR pathways were enriched in gliomas with high MAPK4 expression." (PMID 36999945, 2023).
glioma (continued). "GSEA also showed that signaling pathways (MAPK, PI3K, Focal_adhesion‐PI3K/AKT/mTOR and EGFR) were significantly enriched in gliomas with high MAPK4 expression." (PMID 36999945, 2023). "Further studies of the detailed mechanisms by which MAPK4 exerts its influence on the glioma immune microenvironment will have great significance." (PMID 36999945, 2023). "Considering that immune‐related signaling pathways were enriched in the GSEA, we analyzed the relationship between MAPK4 expression and immune infiltration in gliomas to explore the role of MAPK4 in the immune regulation of glioma." (PMID 36999945, 2023). "Signaling pathways, including the MAPK, PI3K, focal adhesion‐PI3K/AKT/mTOR, and EGFR pathways, were enriched in gliomas with high MAPK4 expression." (PMID 36999945, 2023). "Our work suggests a probable role for MAPK4 in tumor immune regulation and facilitation of glioma progression." (PMID 36999945, 2023). "Our results confirm that MAPK4 promotes glioma progression by facilitating proliferation and migration both in vitro and in vivo, consistent with the previously reported roles of MAPK4 in breast cancer and prostate cancer." (PMID 36999945, 2023). "Metastatic functional state was significantly related to MAPK4 expression in the single‐cell RNA‐seq dataset 1 of glioma." (PMID 36999945, 2023). "MAPK4 was found to promote the proliferation and migration of glioma cells via the AKT/mTOR pathway by bioinformatic analyses and experimental verification." (PMID 36999945, 2023). "MAPK4 functions as a prognostic indicator in glioma and promotes the proliferation and migration of glioma cells via the AKT/mTOR pathway." (PMID 36999945, 2023). "The usefulness of MAPK4 in the diagnosis and prognosis of glioma was analyzed using data from multiple public databases and confirmed in our glioma pathologic specimens." (PMID 36999945, 2023). "MAPK4 expression in gliomas with different clinicopathological characteristics was analyzed based on the TCGA data." (PMID 36999945, 2023). "We further assessed the role of MAPK4 in different molecular subtypes of glioma using the data obtained from the CGGA and TCGA." (PMID 36999945, 2023). "In view of the increased expression of MAPK4 observed in glioma, we evaluated the prognostic value of elevated MAPK4 expression in glioma based on data from the CGGA and TCGA databases." (PMID 36999945, 2023). "Our work demonstrates that MAPK4 is overexpressed in glioma and that it promotes the proliferation and migration of glioma cells via the AKT/mTOR pathway." (PMID 36999945, 2023). "To determine the functional states of MAPK4 in glioma cells at single‐cell resolution, we queried the highly related functional states of MAPK4 using the Cancer Single‐Cell State Atlas (CancerSEA) web server." (PMID 36999945, 2023). "Functional state analyses performed at single‐cell resolution show that MAPK4 expression in glioma correlates with proliferation, metastasis, stemness, inflammation and angiogenesis." (PMID 36999945, 2023). "Inhibition of miR‐125a‐3p was found to partially rescue p38/MAPK phosphorylation and apoptosis by circ‐MAPK4 knockdown, suggesting circ‐MAPK4 as an important modulator in the survival and apoptosis of glioma cells by regulating miR‐125a‐3p/p38/MAPK pathway." (PMID 36705414, 2023). "Pathways such as neutrophil degeneration, cytokine and cytokine receptor interaction, the Toll‐like receptor signaling pathway, interferon signaling and interleukin 6 family signaling were enriched in the gliomas with high MAPK4 expression." (PMID 36999945, 2023). "To investigate the effect of MAPK4 on the growth of intracranial primary glioma in vivo, we established an intracranial glioma model by using luciferase‐labeled MAPK4‐knockdown U87 cells." (PMID 36999945, 2023). "Aberrant expression of MAPK4 also correlated with poor clinicopathological characteristics and disease progression of glioma." (PMID 36999945, 2023).
glioma (continued). "To further validate the expression of MAPK4 in specific cell types, we measured MAPK4 expression in human glioma and para‐tumor tissues by IHC." (PMID 36999945, 2023). "We also analyzed the correlation of MAPK4 expression with immune infiltration and immune checkpoints in glioma." (PMID 36999945, 2023). "Following that, circ-MAPK4 increased glioma cell survival and prevented apoptosis in vitro and in vivo." (PMID 35883576, 2022). "Circ-MAPK4, initially identified from clinical glioma samples, represses apoptosis through the reduction of PARP11 and caspase 3/7/9 cleavage." (PMID 35205610, 2022). "The previous studies have shown that circ-MAPK4 inhibits glioma cell apoptosis through the MAPK signaling pathway by secreting miR-125a-3p." (PMID 36159567, 2022). "Previous studies showed that miR-125a-3p can be also sponged by circ-MAPK4 and circARFGEF1 to regulate cell proliferation and invasion in glioma and LUAC." (PMID 34641879, 2021). "miR-125a-3p is also sponged by lncRNA MALAT1 in hepatocellular carcinoma, circ-MAPK4 in gliomas, circ_0012919 in systemic lupus erythematous and circLMF1 in aortic smooth muscle cells." (PMID 34641879, 2021). "In another study considering the implications of circRNAs in gliomas, circ-MAPK4 was reported to promote glioma cell proliferation both in vivo and through upregulation of the MAPK axis." (PMID 34162394, 2021). "Some other circRNAs (e.g., circEPHB4, circCPA4, circ-MAPK4, circ-POSTN, circNFIX, circSCAF11, circ-U2AF1 and circLGMN are also associated with poor patient prognosis in glioma." (PMID 34745938, 2021). "Another study reported that circ-MAPK4 plays a key role in the survival and apoptosis of glioma cells by regulating the miR-125a-3p and p38/MAPK signaling pathways." (PMID 33494806, 2021). "We verify that circ-MAPK4 is generated from exon 2 of MAPK4 mRNA, and acts as oncogene to promote glioma cell survival and to inhibit apoptosis." (PMID 31992303, 2020). "We performed western blot assays to determine protein expression levels of MAPK signaling pathway in circ-MAPK4 silenced glioma cells." (PMID 31992303, 2020). "Circular RNA MAPK4 (circ-MAPK4) inhibits glioma cell apoptosis via the MAPK signaling pathway by sponging miR-125a-3p in glioma." (PMID 32894165, 2020). "Next, we verified that circ-MAPK4 promoted the survival and inhibited the apoptosis of glioma cells in vitro and in vivo." (PMID 31992303, 2020). "In summary, we determined that circ-MAPK4 regulated cell apoptosis of glioma cells through p38/MAPK signaling pathway by sponging miR-125a-3p." (PMID 31992303, 2020). "Combined with the expected function in inducing glioma cells apoptosis, four miRNAs (miR-125a-3p, miR-217, miR-630, and miR-637) were chosen, which shared binding sites with circ-MAPK4." (PMID 31992303, 2020). "In conclusion: 1.We identify a novel circ-RNA (circ-MAPK4), which is downregulated during neural differentiation and upregulated in glioma tissues." (PMID 31992303, 2020). "To investigate the biological function of circ-MAPK4 in gliomas progression, we designed the circ-MAPK4 siRNAs against the back-spliced sequence of circ-MAPK4." (PMID 31992303, 2020). "Our experimental results suggested that circ-MAPK4 resumes survival and inhibits apoptosis in glioma via p38/MAPK signaling pathway." (PMID 31992303, 2020). "Taken together, circ-MAPK4 can enhance survival of glioma cells through inhibiting cell apoptosis both in vitro and in vivo." (PMID 31992303, 2020). "Transcriptomic profiling data provided by The Cancer Genome Atlas (TCGA) show that MAPK4 expression is correlated with the survival rates in patients with lung cancer, bladder cancer and glioma." (PMID 32711558, 2020). "Higher phosphorylation level of p38/MAPK (p-p38/MAPK) was observed in circ-MAPK4 silenced glioma cells compared with control cells, while total protein levels of p38, ERK, JNK, CREB and the phosphorylation level of ERK remained unchanged." (PMID 31992303, 2020).
glioma (continued). "Here, we showed that a circRNA, circ-MAPK4 is positively correlated with survival of glioma cells by inhibiting their apoptosis." (PMID 31992303, 2020). "TUNEL assay also showed that knockdown of circ-MAPK4 induced apoptosis of glioma cells compared to the control group (P < 0.05)." (PMID 31992303, 2020). "The upregulated circ-MAPK4 “loads” miR-125a-3p to prevent its binding with target oncogenes in gliomas." (PMID 31992303, 2020). "circ-MAPK4 was prominently (P < 0.05) expressed in glioma cell lines (especially U138 and U373) compared with glial cell line (HA1800)." (PMID 31992303, 2020). "Moreover, MAPK4 expression correlated positively with expression of the main immunoinhibitor checkpoint molecules and some chemokines in glioma." (PMID 36999945, 2023). "We speculate that the EGFR signaling pathway acts upstream of MAPK4 in glioma, and future work is aimed at determining whether MAPK4 is regulated by the EGFR signaling pathway." (PMID 36999945, 2023). "Our results demonstrate that MAPK4 facilitates proliferation and migration in glioma cells." (PMID 36999945, 2023). "MAPK4 silencing markedly inhibited the growth of primary glioma." (PMID 36999945, 2023). "Analysis of MAPK4 expression and associated survival in glioma patients was performed based on data obtained from The Cancer Genome Atlas (TCGA) and Chinese Glioma Genome Atlas (CGGA) databases and confirmed in human glioma tissue by immunohistochemistry." (PMID 36999945, 2023). "MAPK4 IHC staining and clinicopathological characteristics of 96 glioma patients." (PMID 36999945, 2023). "Enhanced expression level of MAPK4 was found in glioma tissues than in normal tissues." (PMID 36999945, 2023). "We performed GO enrichment and GSEA to identify the biological function of MAPK4 in glioma." (PMID 36999945, 2023). "MAPK4 expression predicted poor prognosis of glioma patients." (PMID 36999945, 2023). "In vivo, MAPK4 knockdown markedly suppressed the growth of primary glioma." (PMID 36999945, 2023). "MAPK4 blockade might be a promising strategy for the discovery of plausible and attractive drug targets for glioma." (PMID 36999945, 2023). "As the clinical significance of MAPK4 expression in gliomas remain unclear, we analyzed the expression of MAPK4 reported in the TCGA database for glioma tissue obtained from patients whose survival parameters differed." (PMID 36999945, 2023). "The protein levels of MAPK4 were higher in high‐grade glioma compared with low‐grade glioma." (PMID 36999945, 2023). "The growth of orthotopic glioma was suppressed by MAPK4 silencing in this model." (PMID 36999945, 2023). "MAPK4 may participate in immune infiltration and the expression of immune checkpoints in the glioma microenvironment." (PMID 36999945, 2023). "However, circ‐MAPK4 in gliomas was found to increase and coincide with the pathological grade and stage of gliomas by promoting glioma cell survival and inhibiting apoptosis." (PMID 36705414, 2023). "MAPK4 expression was also significantly related to functional states, including stemness, metastasis, differentiation, proliferation and DNA damage, based on the information reported in single‐cell RNA‐seq dataset 3 of glioma." (PMID 36999945, 2023). "Collectively, these results suggest that MAPK4 may be involved in functional states, including proliferation, metastasis, angiogenesis and differentiation in glioma." (PMID 36999945, 2023). "Taken together, our findings demonstrate that MAPK4 plays a promoting role in glioma." (PMID 36999945, 2023). "Immunoblotting was used to analyze the protein level in MAPK4 knockdown glioma cells." (PMID 36999945, 2023). "Circ-MAPK4 has a vital role in glioma cell survival and apoptosis by modulation of miR-125a-3p, which may provide a novel therapeutic target for the treatment of gliomas." (PMID 35883576, 2022). "Such circ-MAPK4-miR-125a3p-p38/MAPK axis is essential for glioma tumorigenesis." (PMID 35205610, 2022).